SF3B1 (splicing factor 3b subunit 1)
Diseases named in the same sentence as SF3B1 in open-access papers (continued):
Sharing a sentence is not in itself a finding about the gene and the disease.
pancreatic ductal adenocarcinoma (5 papers, 2021 to 2024). An infiltrating adenocarcinoma that arises from the epithelial cells of the pancreas. "The splicing factor SF3B1 is recurrently mutated in various tumors, including pancreatic ductal adenocarcinoma (PDAC)." (PMID 37823551, 2023). "Here, we identified that the SF3B1 K700E (SF3B1K700E) mutation is strongly associated with tumor growth in pancreatic ductal adenocarcinoma (PDAC)." (PMID 33932092, 2021).
acute leukemia (4 papers, 2020 to 2025). A clonal (malignant) hematopoietic disorder with an acute onset, affecting the bone marrow and the peripheral blood. "Most studies have claimed that patients carrying an SF3B1 mutation have a significantly better overall survival and a lower likelihood of their disease transforming into acute leukemia compared with patients without SF3B1 mutations." (PMID 32905346, 2020). "Co-mutations varied by subtype; MDS/MPN, NOS, and CMML cases frequently harbored mutations in epigenetic regulators (ASXL1, TET2) and splicing factors (SF3B1, SRSF2, ZRSR2), while acute leukemia cases showed alterations in JAK3, STAT3, and NRAS." (PMID 40806796, 2025).
acute lymphoblastic leukemia (4 papers, 2017 to 2024). Leukemia with an acute onset, characterized by the presence of lymphoblasts in the bone marrow and the peripheral blood. "SF3B1 combined with BRAF mutation might contribute to the development of acute lymphoblastic leukemia." (PMID 32143579, 2020). "Driven by our previous findings on the sensitivity of T cell acute lymphoblastic leukemia (T-ALL) cells to SF3B1 inhibitors, we identified that SF3B1 inhibition blocks T-ALL growth in vivo with no notable associated toxicity." (PMID 35061527, 2022).
breast tumors (4 papers, 2018 to 2023). "SF3B1 mutations in the K700 and K666 residues have been reported also in breast tumors and in pancreatic ductal adenocarcinomas, whereas mutations of residues R625 and K666 were found in uveal melanomas and cutaneous melanomas." (PMID 35406598, 2022). "In breast tumors, SF3B1 mutations were significantly associated with ER-positive disease, often displaying concurrent AKT1 genomic alterations." (PMID 35406598, 2022). "Deleterious mutations in GATA3, an activating SF3B1 mutation (K700E), and an activating AKT1 mutation (E17K) were observed in eight (16.7%), three (6.3%), and three (6.3%) breast tumors, respectively." (PMID 29464067, 2018).
endometrial tumors (4 papers, 2020 to 2024). "This included two lung and two endometrial tumors, which are tumors where SF3B1 and related SUGP1 mutations are documented." (PMID 39390592, 2024). "Third, our in vivo data indicated that SF3B1 inhibitor, PLAD-B, reduces endometrial tumor growth in mice." (PMID 33040078, 2020). "SF3B1 expression was higher in grades I, II, and III endometrial tumors than in normal endometrial tissues." (PMID 33040078, 2020). "Using a tissue microarray, we found that human endometrial tumors expressed more SF3B1 protein than non-cancerous tissues." (PMID 33040078, 2020).
essential thrombocythemia (4 papers, 2020 to 2022). A chronic myeloproliferative neoplasm that involves primarily the megakaryocytic lineage. "In MPN, SF3B1 was found to be mutated in approximately 5% of polycythemia vera (PV) and essential thrombocythemia (ET) patients, and 10% of myelofibrosis (MF) patients." (PMID 35268357, 2022). "Some researchers reported a role of SF3B1 mutations in myelofibrotic progression in patients with polycythemia vera and essential thrombocythemia, whereas others concluded that SF3B1 mutations did not correlate with fibrotic evolution." (PMID 36671709, 2022). "Thirteen genes including ASXL1, U2AF1, SRSF2, SF3B1, and ZRSR2 had significantly higher mutation frequencies in primary myelofibrosis (PMF) compared with essential thrombocythemia and polycythemia vera; this difference distinguished PMF from MPN and likened it to MDS." (PMID 33117717, 2020).
glioblastoma (4 papers, 2022 to 2024). The most malignant astrocytic tumor (WHO grade IV). "Together, we highlight SF3B1 as a potential diagnostic and prognostic biomarker and an efficient pharmacological target in glioblastoma, offering a clinically relevant opportunity worth to be explored in humans." (PMID 35086552, 2022). "Moreover, tumor progression and formation were monitored in response to SF3B1 blockade in two preclinical xenograft glioblastoma mouse models." (PMID 35086552, 2022). "Driver mutations have been found in several RNA-binding proteins (e.g., SF3B1, U2AF1, SRSF2, HNRNPA2B1, SRRM2) in cancers ranging from blood malignancies to glioblastoma, but several questions remain regarding how widely this group of proteins and their targets are involved in cancer." (PMID 35581644, 2022).
lung carcinoma (4 papers, 2017 to 2024). "SLC7A11 can be activated by the transcriptional factor SRY-box transcription factor 2 (SOX2) and the splicing factor 3b subunit 1 (SF3B1) in lung cancer cells." (PMID 39624080, 2024). "In human lung cancer tissues, the overexpression of SOX2 and SF3B1 enhances cell resistance to ferroptosis and correlates positively with SLC7A11 expression." (PMID 39624080, 2024).
schizophrenia (4 papers, 2015 to 2024). A major psychotic disorder characterized by abnormalities in the perception or expression of reality. "Whereas this region includes several genes, our results point to SF3B1 as the likely candidate through which the genetic risk for schizophrenia is conveyed." (PMID 26460480, 2015). "Genes that were associated with brain volumes, depression, and schizophrenia or bipolar disorder includedAC011997.1,AKT3,BANK1,BOLL,DCC,HSPD1,HSPE1,HSPE1-MOB4,MOB4,PLCL1,RFTN2,SF3B1, andTRPS1." (PMID 40800518, 2024). "Particularly interesting are SF3B1, DLG2 and FOXP1 because of the strong association for the SF3B1 in the PGC meta-analysis and the previous evidence implicating DLG2 and FOXP1 in schizophrenia and other neurodevelopmental disorders." (PMID 26460480, 2015). "Furthermore, SF3B1 is involved in adult neurogenesis, acts as a transcription factors and is associated with PQBP1, which is linked to neurodegenerative disorders and intellectual disability, an endophenotype involved in schizophrenia." (PMID 26460480, 2015).
sideroblastic anemia (4 papers, 2022 to 2025). "The Splicing Factor 3B subunit 1 (SF3B1) mutation corresponds to most “sideroblastic anemias” of the previous classification and is considered MDS-related." (PMID 37444390, 2023). "Moreover, in contrast to canonical SF3B1 mutations, E592K induces a unique RNA missplicing pattern, retains an interaction with the splicing factor SUGP1, and preserves normal RNA splicing of the sideroblastic anemia genes TMEM14C and ABCB7." (PMID 37090662, 2023).
bladder cancer (3 papers, 2020 to 2024). "However, no subsequent studies have analyzed the aberrant splicing events caused by SF3B1 mutations in bladder cancer." (PMID 39132499, 2024). "We first downloaded the mRNA expression data of normal and bladder cancer tissues from TCGA database and analyzed the mRNA expression of a total of 97 RNA splicing proteins (including SRSF family, RBM family, HNRNP family, SF3B1, PRMT5, PUF60, U2AF1, and ZRSR2) between normal and carcinoma tissues." (PMID 33117697, 2020).
cervical carcinoma (3 papers, 2016 to 2024). A carcinoma arising from either the exocervical squamous epithelium or the endocervical glandular epithelium. "This is the first study that indicated the potential involvement of SF3B1 in cervical cancer development as the expression levels were significantly elevated in cervical cancer samples compared with the control group, but also in precursor lesions." (PMID 40729294, 2024). "While the role of SF3B1 in cervical cancer development is newly reported here, its involvement in other cancers and cellular processes indicates its broader oncogenic potential." (PMID 40729294, 2024). "SF3B1 could be a potential biomarker for cervical cancer, while DCP2 may serve as a viral infection indicator." (PMID 38790189, 2024). "In this context, this study aimed to evaluate the potential of the investigated factors EIF4G3 and SF3B1, including the methylation status of CpG islands around gene promoters and their expression in cervical cancer and precursor lesions, and to assess their prognostic potential." (PMID 40729294, 2024). "MCL-1 splicing is partially regulated by SF3B1, and inhibition of SF3B1 reversed the dominant splice isoform from anti-apoptotic MCL-1L to pro-apoptotic MCL-1S in NSCLC and cervical carcinoma cell models." (PMID 27613060, 2016). "By identifying new factors such as SF3B1 and EIF4G3, which show increased mRNA expression and altered methylation patterns in cervical cancer and precursor lesions, the research underscores the potential of these genes as biomarkers for early detection and diagnostic precision." (PMID 40729294, 2024).
diabetes (3 papers, 2021 to 2025). "In individuals with bone marrow syndrome, mutations in TET2 and SF3B1 genes are associated with a more severe prognosis, and the presence of diabetes also amplifies the frequency of these genetic alterations." (PMID 39926430, 2025). "TET2 and SF3B1 mutations have been found to present more frequently in the blood cells of MDS patients who also have diabetes." (PMID 40336178, 2025). "Low SF3B1 expression levels were associated with arterial hypertension (AHT) and type 2 diabetes mellitus (T2DM) in this patient cohort." (PMID 34857016, 2021). "Furthermore, patients with bone marrow syndrome who also have diabetes exhibit a higher mutation rate of the 10-11 translocation 2 (TET2) and splicing factor 3b subunit 1 gene (SF3B1), which correlates with a more severe prognosis." (PMID 39926430, 2025).
iron overload (3 papers, 2023 to 2025). "Iron overload is prevalent in MDS, especially in cases with SF3B1 mutations." (PMID 40124717, 2025). "Iron overload results from a combination of these factors together with the disease-associated ineffective erythropoiesis, that is seen especially in MDS cases with SF3B1 mutations." (PMID 38835379, 2024).
liver cancer (3 papers, 2018 to 2026). An epithelial or non-epithelial malignant neoplasm that arises from the liver. "Collectively, SF3B1 expression is increased in liver cancer, which may be the primary cause of induction of abnormal autoimmune-response." (PMID 29954402, 2018). "Importantly, using mouse models of liver cancer, we show that RBM39 and SF3B1 inhibitors are effective in targeting both preneoplastic lesions and aggressive tumours expressing oncogenic RAS." (PMID 41986348, 2026). "Western blot analysis showed that SF3B1 expression was significantly increased by about 2- or 3-fold (p < 0.05) in HCC tissues of H-ras12V transgenic (Hras12V-Tg) mice, another mouse model of liver cancer, compared to normal liver tissues." (PMID 29954402, 2018).
meningeal melanoma (3 papers, 2018 to 2024). "The presence of SF3B1–, EIF1AX–, or BAP1–mutation or complex copy number variations indicate aggressive behavior consistent with meningeal melanoma." (PMID 36497333, 2022). "Furthermore, some additional molecular alterations, such as SF3B1, EIF1AX, and BAP1 mutations, confer a significant aggressive course in meningeal melanoma, while both primary diffuse leptomeningeal melanocytosis or melanomatosis are often NRAS mutated and rarely BRAF mutated." (PMID 39061148, 2024).
myeloid leukemia (3 papers, 2021 to 2023). A clonal proliferation of myeloid cells and their precursors in the bone marrow, peripheral blood, and spleen. "Despite the potential of H3B-8800 to treat myeloid leukemia and other cancer types hallmarked by SF3B1 mutations, the molecular mechanism underlying its preferential lethality towards spliceosome-mutant cancer cells remains elusive." (PMID 34681880, 2021).
neuroblastoma (3 papers, 2016 to 2024). Neuroblastoma (NB) is the most common solid, extracranial childhood tumor. "SF3B1 KD caused substantial decrease of exon 7 inclusion in SH-SY5Y cells derived from neuroblastoma patients (~31.4%) (lane 6) and HEK293T cells (~14.6%) (lane 9)." (PMID 33317029, 2020). "The data showed that JMJD6 co-dependency genes were significantly and positively correlated with spliceosome/mRNA splicing (i.e. RBM39, SF3B1), ubiquitin-mediated proteolysis and endocytosis and a number of 17q25 genes, which mirrored the pathway network of 17q essential genes in neuroblastoma." (PMID 38488852, 2024).
Richter syndrome (3 papers, 2020 to 2024). Transformation of chronic lymphocytic leukemia into aggressive non-Hodgkin's lymphoma, usually diffuse large B-cell lymphoma (immunoblastic or centroblastic variant). "Amplifications on chromosome 7 are frequent CNV events in CLL and a common downstream CNV event of SF3B1 mutation following transformation of CLL to Richter Syndrome." (PMID 39194178, 2024). "Last but not least, we would like to emphasize the value of further investigation into the response rates to RG7388 in groups of SF3B1 wild-type versus mutant patients with Richter syndrome." (PMID 37511096, 2023).
Splenomegaly (3 papers, 2016 to 2023). Abnormal increased size of the spleen. "In addition, mutations in TET2 and SF3B1 were associated with an older age, SF3B1 with higher platelet counts, and ASXL1 with palpable splenomegaly." (PMID 37745842, 2023).
Thrombocytopenia (3 papers, 2021 to 2023). A reduction in the number of circulating thrombocytes. "Spliceosome mutations (SF3B1, SRSF2, and U2AF1) were enriched in individuals with thrombocytopenia compared with their matched controls (3.4% vs 1.1%; P = 0.007)." (PMID 36698617, 2023). "Although the prevalence of CH was not increased in thrombocytopenia cases compared with their controls (37.9% vs 39.3%; P = 0.639), mutations in spliceosome genes (SF3B1, SRSF2, U2AF1) were significantly enriched in thrombocytopenia cases (P = 0.007)." (PMID 36698617, 2023).
triple-negative breast carcinoma (3 papers, 2020 to 2022). An invasive breast carcinoma which is negative for expression of estrogen receptor (ER), progesterone receptor (PR), and human epidermal growth factor receptor 2 (HER2). "Among them, E7107 has been shown to enhance antitumor response when combined with the proteasome inhibitor, bortezomib, in triple-negative breast cancer, thus highlighting the possible usage of mutant SF3B1 inhibitors in combination therapies." (PMID 32354150, 2020). "Hypomethylation within this gene in CLL patients with SF3B1 mutation has been previously reported and it has been recently shown that BCL9 and BCL9L promote tumorigenicity in a triple negative breast cancer mouse model through immune-dependent (TGF-β) and immune-independent (Wnt) pathways." (PMID 34502260, 2021).
bipolar disorder (2 papers, 2024 to 2025). A disorder of the brain that causes unusual shifts in mood, energy, activity levels and the ability to carry out day-to-day tasks. "In addition, CNNM4 and SF3B1 also belong to the bipolar disorder GWAS catalog, reinforcing the confidence level of MAAT’s results." (PMID 39905509, 2025).
colon cancer (2 papers, 2018). "Therefore, the response of colon cancer cells to IGG was distinguishable from changes associated with the SF3B1 inhibitor PB." (PMID 29338026, 2018). "We considered that the G1 and G2/M arrests reported in response to SF3B1 inhibitors were detected using WiDr colon cancer cells and Chinese hamster ovary (CHO) cells, respectively." (PMID 29338026, 2018).
congenital sideroblastic anaemia (2 papers, 2015 to 2022). "Therefore, we prepared CD34+ BM cells from four SF3B1-mutated MDS-RS patients (MDS1, TP1; MDS2, TP1; MDS3; MDS4) and one congenital sideroblastic anaemia patient (MDS5 with ALAS1 mutation), which was used as a control." (PMID 26643973, 2015). "The diagnosis could also be related to the presence or the absence of an SF3B1 mutation, which is most often reported in MDS and is not found in acquired reversible or congenital sideroblastic anemias." (PMID 35885655, 2022).
dysplasia (2 papers, 2022 to 2025). A usually neoplastic transformation of the cell, associated with altered architectural tissue patterns. "Recent studies report SF3B1 mutation identifies a homogeneous subgroup regardless of bone marrow sideroblasts or dysplasia lineages." (PMID 36224330, 2022).
gastric cancer (2 papers, 2021 to 2025). A primary or metastatic malignant neoplasm involving the stomach. "Pladienolide B has been discovered as a potent and specific SF3B1 inhibitor with anti-proliferative effects in CLL and gastric cancer." (PMID 33648524, 2021).
invasive breast carcinoma (2 papers, 2015 to 2017). A carcinoma that infiltrates the breast parenchyma. "Four patients with invasive breast carcinoma among 27 with various carcinoma types carried the SF3B1 K666E/M/N/Q/T hotspot mutation." (PMID 29383138, 2017).
iris melanoma (2 papers, 2020 to 2021). A uveal melanoma that arises from the iris. "SF3B1 mutations, correlated with late onset metastases, have been found more often in posterior UM compared to iris melanoma." (PMID 33396957, 2020). "Iris melanoma harbor GNAQ, GNA11 and EIF1AX mutations while BAP1 mutations and mutations in SF3B1 are less common or rare." (PMID 33396957, 2020).
leukocytosis (2 papers, 2022 to 2025). "Accordingly, CMML patient harboring CSF3R T618I mutation had a myeloproliferative phenotype with leukocytosis but showed concomitant dysplastic features, probably derived from the presence of double splicing-factor mutations, SRSF2 P95L and SF3B1 K666N." (PMID 39907800, 2025).
lymph node metastasis (2 papers, 2021 to 2023).
lymphoma (2 papers, 2023 to 2024). A malignant (clonal) proliferation of B- lymphocytes or T- lymphocytes which involves the lymph nodes, bone marrow and/or extranodal sites. "Subset #4 is the largest subset of mutated IGHV CLL and is characterized by lower CD38 expression and the absence of NOTCH1- and SF3B1 mutations, while subset #8 has a higher risk for transformation into an aggressive lymphoma (Richter transformation)." (PMID 38835970, 2024).
neutropenia (2 papers, 2021 to 2022). A decrease in the number of neutrophils found in the blood. "Finally, 68% of the tested cases displayed at least one somatic mutation, most commonly SF3B1, TET2, ASXL1, and SRSF2, associated with older age, presence of neutropenia, and lower response to ESAs." (PMID 35392224, 2022).
pancreatic adenocarcinoma (2 papers, 2021 to 2022). "Other genes often mutated in subclones are the splicing factor SF3B1 and, in breast and pancreatic adenocarcinomas, the tumor suppressor SMAD4." (PMID 33831375, 2021).